CD4 (CD4 molecule)
Diseases named in the same sentence as CD4 in open-access papers (continued):
Sharing a sentence is not in itself a finding about the gene and the disease.
infection (continued). "In particular, studies in transplantation patients and in adults with primary human CMV (HCMV) infections have confirmed the vital role that HCMV specific CD4+ T cells play in controlling symptomatic disease." (PMID 32509591, 2020). "Brains of SINV-infected mice defective in IFN-γ signaling had both fewer CD4+ T cells and CD8+ TRM cells than WT mice, indicating a need for IFN-γ to promote the residence of TRM cells in the brain after infection." (PMID 31963302, 2020). "This inflammation recruits immune cells, including CD4+ T cells, therefore consolidating HIV′s primary target of infection." (PMID 33172001, 2020). "The ratio of CD4+ to CD8+ cells shifted from an approximate 1:1 ratio (46.7:42.7, week 0) before infection to a 1:2.5 ratio (24.9:62.9, week 13) during the chronic disease phase." (PMID 32154190, 2020). "G2-S16 PCD exerts anti-HIV activity at an early stage of viral replication, by blocking gp120/CD4/CCR5 interaction, and providing a barrier against infection for long periods of time." (PMID 33321835, 2020). "GC formation and plasmablast, CD4+ TFH and TFR cell differentiation at 7.5 and 13.5 days post infection were equivalent between all groups of mice." (PMID 33519801, 2020). "We found that the chief sources of IFN-γ in the brain during infection were CD4+ and CD8+ T cells, with minimal contribution from NK cells, an important source of the cytokine during early stages of acute infection." (PMID 33108405, 2020). "The mean CD4 count for PWLWH was within the normal range [668 cells/mcL (range 356–1,505)] and most women had a fully supressed infection with plasma HIV loads of <40 copies/mL at the time of sampling [79% (42/53)]." (PMID 33643930, 2020). "Infection with M. bovis and BCG stimulated the differentiation of naïve CD4+ T cells into subsets of Th17 and Treg in the mouse model with the corresponding cytokine atmosphere, and COX-2/PGE2 signaling mediated these processes." (PMID 32023904, 2020). "A temporal decrease in the percentage of CD4+ cells on day 6 post-infection and a significant increase in the percentage of CD8+ cells was observed in the second week of infection." (PMID 33324583, 2020). "This suggests that the expanded Tregs enable parasite replication by interfering with the CD4 TH1 and TFH responses known to be critical for controlling blood stage infection." (PMID 32043415, 2020). "To further define the role of T cells in the observed immunopathology of the lung after IV infection, we investigated the phenotype and functional properties of CD8+ and CD4+ T cells isolated from mediastinal lymph nodes (mLN) or from BALF." (PMID 32226027, 2020). "Both CD4+ and CD8+ SARS-CoV-specific memory T cells have been shown to persist in convalescent SARS-CoV patients at low frequency up to six years post-infection." (PMID 32499988, 2020). "Certain bovine respiratory complex pathogens like Mycoplasma bovis strongly inhibit lymphoproliferation of CD4+ and CD8+ T cells during infection." (PMID 33187270, 2020). "We assessed CD3+CD4+IL17+ cells and results demonstrate that chronic ethanol consumption strongly reduced lymphocytes and IL-17 production in the site of infection after 24 hr of infection." (PMID 32701055, 2020). "These SIV-infected cohorts demonstrated a decline in CD4+ T cell counts from pre-SIV infection through acute and chronic SIV-infection (with mean CD4+ T cell counts of 758 cells/μl for pre-, 325 cells/μl acute-, and 127 cells/μl chronic-SIV timepoints)." (PMID 32426577, 2020). "Luo and colleagues also reported lower cell counts and impaired function of CD4+ T cells, CD8+ T cells and NK cells in kidney transplant recipients with infection." (PMID 32993687, 2020). "Further, elevated E6-specific CD4+ IFN-γ+IL-17+ T-cells pre- and post-infection positively correlated with protection against Mtb." (PMID 32545304, 2020).
infection (continued). "It was reported that IL-27RA−/− mice have an exaggerated lung immunopathology after the infection with IFV, that correlated with increased levels of CD4+ and CD8+ T cells producing IL-17 and a strong neutrophil infiltration." (PMID 33133080, 2020). "Multiple other independent studies established that SARS-CoV specific memory CD4+ and CD8+ T cells persisted for up to 2 years after infection." (PMID 33013871, 2020). "IFN-γ, an important product of natural killer (NK) cells and CD4+ and CD8+ T cells, exerts its antiviral effects by inducing IFN-stimulated genes (ISGs), but also by modulating the immune response to infection." (PMID 31963302, 2020). "CXCL9, CXCL10, and CXCL11 are chemokines which are able to induce chemotaxis in CD4+ Type-1 helper (Th1) and CD8+ cytotoxic lymphocytes as well as in natural killer cells and natural killer T cells, directing them to sites of infection and inflammation." (PMID 32328494, 2020). "(F) Comparison of the proportions of Tem (CD4+CD45RO+CD45RA-CCR7-CD62L-) and Tcm (CD4+CD45RO+CD45RA-CCR7+CD62L+) among uninfected Tm and PRE cells in PBMCs and ETs reveals preferential infection of Tem in both compartments." (PMID 32452381, 2020). "Thus, the Ag-specific CD4+ T cell response contracted more quickly during the secondary response than the primary; however, this may be expected due to more rapid clearance of Lm during secondary infection." (PMID 32983171, 2020). "In addition to this cell-free infection process, it is now well established, at least for infection of CD4+ T cells, that HIV-1 can be transmitted and spread through direct cell-to-cell transfer, and this route of infection may be the predominant mode of propagation in infected patients." (PMID 33348900, 2020). "(A, B) The emigrating cells were harvested and stained with (A) anti-CD1a and anti-HIV-1 mAbs for DCs, and (B) anti-CD3, anti-CD4, and anti-HIV-1 mAbs for CD4+ T cells and the level of infection was assessed by flow cytometry (N = 7–8)." (PMID 32876566, 2020). "IL-2 induces CD4+ and CD8+ T cell proliferation and differentiation and stimulates the growth of memory T cells during primary infection." (PMID 33133057, 2020). "The study uncovered a complex process where IFN-γ producing Th1 cells secrete IL-10 in the early stages of infection and counteract NA-mediated activation of latent TGF-β in flu-specific CD4+ T cells." (PMID 32974217, 2020). "At 18 days post infection CD3+CD8+CD43+ T cells and CD3+CD4+CD43+CD62L- T cells were sorted from the spleen of FV-infected DEREG mice and from infected DEREG mice treated with DT plus anti-PD-L1/Tim-3 antibodies." (PMID 32226027, 2020). "We monitored the T cell profile, including Th1, Th2, Th17 and Treg cells, in the CD4+ T cells from PBMC and lung tissue on different days post infection." (PMID 33180882, 2020). "Salmonella-specific CD4 and CD8 T cells are generated during infection with attenuated bacteria in mice." (PMID 32269573, 2020). "Differences in the TCR repertoire between spleens and lungs suggest that populations of CD4+ and CD8+ T cells vary from the spleen to the site of infection of hRSV (lungs)." (PMID 32093256, 2020). "However, information regarding whether ICOS expression by memory CD4+ T cells has a direct effect on the ability of these cells to adopt a Tfh phenotype in response to antigen re-challenge is limited, specifically in the context of infection." (PMID 32348365, 2020). "In the acute phase and early stage of infection, the content of HIV-1 DNA in CD4 cells of intestinal lymphoid tissue was 10 times higher than that in peripheral blood." (PMID 33302895, 2020). "Therefore, it is hypothesized that the persistent activation of both TLR 7 and 9 results in the depletion of monocytes, macrophages, CD4+ T cells, and IFN-γ, rendering host cells susceptible to infection and the disease progression of HIV and Mtb, especially in HIV-Mtb coinfection." (PMID 32858917, 2020).
infection (continued). "It has been described that both CD4+ and CD8+ T cells can contribute to the clearance of the virus during an infection." (PMID 32093256, 2020). "The second mechanism involves interleukin-12 release by the macrophages, in response to the infection, to allow synthesis of IFN-γ by Toxoplasma-specific CD4+ and CD8+ T-cells through a Th1 immune response." (PMID 32031519, 2020). "From the same time point after challenge (20 h post-infection), we also analyzed the IFN-γ production from effector CD4 T cells by flow cytometry." (PMID 32651371, 2020). "As with other intracellular pathogens, protection from infection requires the induction of T helper 1 (TH1) responses, characterized by IFN-γ producing CD4+ T cells and cytotoxic CD8+ T cells." (PMID 33363134, 2020). "On day 8 after infection, a decreased percentage of Bcl-6hiCXCR5+ TFH cells was observed among GP66–77 tetramer-positive CD4+ T cells originating from Ezh2fl/fl ERT2-Cre mice compared with that of cells of WT origin." (PMID 30842630, 2020). "While CD80+ T lymphocytes are essential for protection after intraperitoneal infection, both CD4+ and CD8+ T lymphocyte subpopulations play a substantive protective role in the case of a peroral, i.e. natural route of infection." (PMID 32539803, 2020). "Based on these findings, higher infusion of TIL cells and the percentage of CD8+ TIL, less infusion of CD8+PD1+ TIL and CD4+FoxP3+ TIL, and infection with HPV and fever are potential factors predicting the response to TILs and anti-PD1 combination therapy." (PMID 32964058, 2020). "Studies compared IAV or IBV patients with healthy subjects, elevated serum IL-6, IL-8 level and decreased CD3+CD4+, CD3+CD8+, NK counts related to patients infection." (PMID 32196410, 2020). "First, we determined the presence of viral DNA and R-U5 transcripts in CD4 T cells sorted from peripheral blood and LNs from RMs treated with a cocktail of antiretroviral ART drugs at week 6 post infection." (PMID 31723251, 2020). "Whereas CD8+ T cells are essential for protection against an intraperitoneal infection, both CD4+ and CD8+ T lymphocyte subpopulations play a substantive protective role in the oral route of infection entry." (PMID 32539803, 2020). "The addition of rIL-27 to L. major lysate-stimulated CD4+ T cells collected at the eighth week post-infection from L. major-infected C57BL/6 mice enhances the population of IL-10+ IFN-γ+ CD4+ cells and IL-10+ IFN-γ− CD4+ cells." (PMID 32849534, 2020). "CD4+ T cells were TCR-activated and treated with TLR7/8/9 ligands for 24 h before infection with NLENG1-IRES-eGFP virus." (PMID 31919342, 2020). "Furthermore, the decrease in Treg frequencies in JA142-infected pigs could be attributed to phenotypic plasticity, which resulted in most of the naïve CD4+ T cells differentiating into effector cells, such as Th1 and Th17, after being antigenically stimulated during the acute infection." (PMID 32404209, 2020). "Of note, in previous SARS-CoV epidemics, specific polyfunctional CD4 and CD8 T-cells were present several years after infection." (PMID 33178207, 2020). "Possible mechanisms of infection include the binding of HIV envelope glycoproteins to the highly expressed CCR5/α4β7 receptor on Vγ9Vδ2 T cells, leading to infection through a CD4-independent pathway." (PMID 33348583, 2020). "CD4 and CD8 T cells were activated in the MLN after infection with M. tuberculosis as measured by the expression of CD44 as compared to uninfected controls." (PMID 33193338, 2020). "The PRE cells also had higher CD4 MSI than the infected cells, consistent with downregulation of CD4 upon infection." (PMID 32452381, 2020). "First, we used as targets the CD4+T CEM cell line that are resistant to NK cells (CEM-NKr) infected with HIV-1 (JR-CSF) as target, which infection level reaches 30–40% of the total cell population after 3 days, as we have shown." (PMID 32582208, 2020).
infection (continued). "Infection induces mainly an IL-13 secreting Th2-mediated response, and some IFN-γ - secreting CD4+ and CD8+ T cell responses." (PMID 33042146, 2020). "Because CD4 and CD8 T cells also play an important role in adaptive immune responses, we assessed changes in the CNS levels of Cd4, Cd8a, and Cd8b mRNAs after infection as indicators of T cell infiltration and retention." (PMID 32047134, 2020). "Overall, lung CD4+ and CD8+ T cells were increased in RSV re-challenged mice compared to mice 25 days post RSV primary infection." (PMID 33123150, 2020). "Memory CD8+ T cells are a major component of immunity against intracellular pathogens, like viruses, and CD4+ T cells are necessary for the development of memory CD8+ T cells during immunity and pathogen infection." (PMID 32517220, 2020). "Approximately 70% of CD4 and CD8 T cells from mice 30 days after infection with M. tuberculosis resided in the lung parenchyma." (PMID 33193338, 2020). "IFN-γ-producing T cells play a key role in the protective immunity against B. abortus and IL-12 is reported to possess a profound effect on the stimulation of CD4+ T cells and NK cells in producing IFN-γ that overall contribute in the control of infection." (PMID 32482929, 2020). "The proportion of infection-elicited IFNγ+, IL4+ and polyfunctional CD4+ T-cells among influenza A/H1N1-infected patients were significantly greater than vaccine-elicited CD4+ T-cells against influenza A/H1N1 (p = 0.033, 0.026 and 0.042 respectively)." (PMID 32572168, 2020). "At the initial steps of infection, HIV-1 envelope proteins at the surface of the virus bind to CD4 receptors, mainly CCR5, initiating autophagy in CD4 T cells." (PMID 32354054, 2020). "Assessment of T cell responses at 10 dpi showed a decrease in the number of total and activated (CD44hi) CD4+ and CD8+ T cells at the site of infection (BAL and lung) in triclosan exposed mice compared to controls." (PMID 33373420, 2020). "Notably, the Salmonella-specific CD4+ T cell response was significantly increased in mice lacking a thymus compared to sham control mice, indicating that, although there were likely a sufficient number of T cells available to control infection, they were incapable of doing so." (PMID 32722409, 2020). "To test these alternative models, we depleted CD4 or CD8 T cells in Batf3−/− mice and evaluated infection with RHΔku80Δrop5 parasites." (PMID 32669460, 2020). "Mice with NK cell depletion had a significantly higher proportion of CD4+CD25+Foxp3+ T cells (Tregs) than control mice at day 3, and this enhanced frequency of Tregs were persisted till day 7 after secondary infection in both spleen and lung tissues." (PMID 32626664, 2020). "In the context of Brucella pathogenesis, it has been demonstrated that B. abortus is capable of inducing IL-10 production by CD4+CD25+ T cells, which impairs macrophage bactericidal activity, favoring bacterial survival and persistence of infection." (PMID 32298378, 2020). "The study found robust CD4+ and CD8+ memory T cell response in severe cases (n = 14) than mild (n = 28), suggesting long-lasting memory of these cells to keep the infection in check." (PMID 33335518, 2020). "Sustained protective immunity in the nasal cavity, generated by natural infection or immunization with a wP vaccine, was strongly correlated with IFN-γ-producing and, to an even greater extent, IL-17-producing CD69+ CD4 TRM cells." (PMID 33096737, 2020). "Little change was seen in the CLNs, with less than 10% of CD4+ T cells, less than 20% of CD8+ T cells, and 20–40% of NK cells producing IFN-γ at any time after infection." (PMID 31963302, 2020). "The frequency of PD1+ Ag85B and TB10.4-specific CD4 and CD8 T cells increased during infection with M. tuberculosis and remained elevated at the late time points of infection." (PMID 33193338, 2020).
infection (continued). "In the brain, the percentage of CD4+ and CD8+ T cells producing IFN-γ increased over the course of infection, going from approximately 40 to 60% at 5 and 7 DPI to over 80% at 10, 14, and 90 DPI." (PMID 31963302, 2020). "While the defects in T cell responses in this study were not drastic, the numerical defects observed in T cell responses at the site of infection were consistent, occurring in both the BAL and the lung, and found in both CD4+ and CD8+ T cell subsets." (PMID 33373420, 2020). "In contrast, memory CD4+ T cells expressing CD57, a marker of terminally differentiated cells and T follicular helper (Tfh) cells, readily supported productive infection." (PMID 32353080, 2020). "An attachment inhibitor that targets HIV-1 gp120 and blocks its binding to CD4+ T cells, BMS-62652942, was added to prevent new rounds of infection." (PMID 32792548, 2020). "Using the LCMV model of viral infection in mice, it has been shown that, at the peak of infection, Teff cells to the dominant MHC-II restricted GP66–77 epitope are higher affinity whereas cells transitioning to memory CD4+T cells have a lower affinity." (PMID 33120989, 2020). "Epicutaneous infection with the wild-type and Δplc strains induced mild thickening of the epidermis and infiltration of CD45+ leukocytes, Gr-1+ granulocytes, and CD4+ T cells." (PMID 33082376, 2020). "Our results indicate that galectin-3 binds to gp120 and CD4 proteins via the CRD, further facilitating HIV-1 CRF07_BC infection." (PMID 32485969, 2020). "As autoimmune response and infection are both able to induce OLP, to better mimic it in vitro, we treated HOKs with LPS or activated CD4+ T cell supernatants to establish OLP models." (PMID 31942011, 2020). "In the lung draining TBLN at 4 days post-infection (DPI), proliferating CD4+ T-cells were identified." (PMID 33391267, 2020). "Encouraged by the previous findings, we went one step further to quantify the production of viral particles from CD4+ T cells infected with TF and NT viruses in cultures treated separately with IFN-α and MVC before infection." (PMID 32066770, 2020). "We depleted both CD4+ and CD8+ T cells starting 4 days before MmuPV1 infection on ears and tails and then continuing depletion until the endpoint of 7 weeks post-infection while following papillomatosis in both K17KO and WT mice." (PMID 31968015, 2020). "In conclusion, higher infusion of TIL and CD8+ TIL, lower infusion of CD8+PD1+ TIL and CD4+FoxP3+ TIL, and infection with HPV and occurrence of fever are potential factors for predicting the clinical response to combination therapy of TILs and anti-PD1." (PMID 32964058, 2020). "The frequency of CD4+CD25+FoxP3+ Tregs in peripheral blood and spleen was significantly higher in the rAAV-IL2 treated group than in the control group throughout the infection." (PMID 32111171, 2020). "Colon biopsies of post-infection IBS patients show that intestinal endocrine cells (ECs) increase more than five times in number, while lamina propria T cells (CD3, CD4 and CD8) double in number." (PMID 33206753, 2020). "To verify this, we treated infected CD4 TCM with 66nM FTY720 and ART (1μM Raltegravir and 0.5μM Nelfinavir) for 72 hours in order to prevent further rounds of infection and assessed p24 (viral release) by ELISA." (PMID 32790802, 2020). "When comparing the effector molecule levels after re-challenge with that observed at 21 days post 1st infection, the intensity of IFN-γ production was increased or maintained at high levels in CD4+ and CD8+ TEM subsets (P0 & P5) in vaccinated groups." (PMID 33414785, 2020). "By using an acute lymphocytic choriomeningitis virus (LCMV) infection model, we observed elevated expression of EZH2 in early-activated virus-specific CD4 T cells." (PMID 32999031, 2020).